CD8A (CD8 subunit alpha)
Diseases named in the same sentence as CD8A in open-access papers (continued):
Sharing a sentence is not in itself a finding about the gene and the disease.
tumor (continued). "Following depletion of CD8+ T cells in tumour-bearing mice using anti-CD8a neutralizing antibody, the anti-tumour effect of anti-BTNL2 treatment was completely abolished, indicating that CD8+ T cells are the major tumour-cytotoxic cell following BTNL2 blockade." (PMID 35017553, 2022). "Interestingly, the treatment with mito induced the infiltration of cDC1s (CD8α+ DCs) into the tumor, which was further increased by the addition of oHSV." (PMID 35163675, 2022). "Similarly, co-treatment with PD-1 mAb and sheEF2K further decreased the tumor volume and tumor weight compared with sheEF2K or PD-1 mAb alone treatment, and CD8α blockade rescued the decreased tumor growth induced by this combination." (PMID 35347072, 2022). "The hybrid-DNA nanostructures could efficiently co-deliver the antigen peptide and CpG to CD8α+ DCs in the tumor-DLN, promoting potent antigen presentation to regulatory T cells via DC activation." (PMID 34138315, 2021). "Of note, the CD8α+ CD103+ cDC1 lineage of cDCs is superior in antigen cross-presentation, a process of presenting exogenous antigens on major histocompatibility complex (MHC) class I to activate CD8+ T cells and are thus particularly important for producing CD8+ T cells that can kill tumor cells." (PMID 33614913, 2021). "We found that tumor purity was only negatively related to three immune genes, namely, CD8A (R = −0.18, p = 1.06 e-06), CXCR2 (R = −0.18, p = 2.90 e-07), and TNFRSF14 (R = −0.21, p = 2.58 e-09), but not to other immune-related genes, including the well-known PD1, PD-L1, and CTLA4." (PMID 34925437, 2021). "In addition, the expression of MHC class II molecules, such as HLA-DR, in tumor tissue has been linked to the presence of tumor-infiltrating lymphocytes (TILs) and high expression of CD4, CD3D, and CD8A." (PMID 34439290, 2021). "This meta-analysis study revealed the importance of both tumor-cell-intrinsic (e.g., tumor mutational burden and PD-L1 expression) and tumor-cell-extrinsic (e.g., CXCL9, CD8A, CXCL13, CCR5 and T cell inflamed gene expression signature) factors underpinning ICB sensitization." (PMID 34092233, 2021). "Importantly, the combination with STING agonist further facilitated the migration of mature CD8α+ dendritic cells to the lymph nodes and the infiltration of TILs within tumors, resulting in primary tumor regression and pulmonary metastasis eradication in mice." (PMID 34589084, 2021). "Indeed, tumor sizes in mice that received CD8α ALN-1 quickly caught up with those in control animals." (PMID 34772757, 2021). "Thus, we conclude that CD8α co-stimulation with TEG011 improves overall in vivo tumor control, T cell persistence, and infiltration of CD8-expressing TEG011 cells." (PMID 34759930, 2021). "In addition, this combination treatment enhanced the expression of CD8α and CD11c in tumor tissues compared with IgG, NPs-Stattic, and NP-Stattic-IL20RA plus IgG treatment, respectively." (PMID 33456560, 2021). "Type I IFN signaling plays a crucial role in innate immune responses, as evidenced by deficient antigen presentation and reduced T cell priming in IFNαR knockout CD8α+ dendritic cells, and the accelerated metastatic spread of tumor cells in IFNαR knock-out mice." (PMID 34070756, 2021). "Here, we systematically screened four hinges with three neoantigen-specific TCRm scFvs targeting different HLA allele backgrounds (A*02:01, A*03:01, B*07:02) and identified the CD8α hinge as the most sensitive for our given target class of tumor-specific MANA-pHLA complexes." (PMID 34489470, 2021). "In addition, increased expression of CD8α, CXCL9, CXCL10, Granzyme A (GZMA), Granzyme B (GZMB), and IFN-γ was observed in Six1-deficient tumor tissues." (PMID 34782761, 2021). "Additionally, average V/J pairing usage frequencies in the tumor show oligoclonal expansion of CD8+ T cells for certain TCRB V/J sequences after treatment with OVA + CD8α ALN-1." (PMID 34772757, 2021).
tumor (continued). "However, despite these mutations, this construct failed to unfold its observed in vitro cytotoxic potential in an in vivo model, while a shorter but less structured CD8α spacer CAR showed complete tumor clearance." (PMID 32849600, 2020). "Whilst some other immune cells such as dendritic cells may express CD8-α, in the context of the other available data, this suggests that CD8 T cells mediate the GDF15 induced reduction in TRAMP tumor growth and development." (PMID 32502202, 2020). "Of particular notice, treatment of MC38 cells with SFV-IL12 results in tumor-infiltrating monocytic myeloid-derived suppressor cells (M-MDSCs) displaying increased expression of CD11c, CD8α, CD40, and CD86 in the presence of an intact, endogenous host type-I interferon (IFN-I) system." (PMID 32050597, 2020). "We obtained results on the correlation between TPPP3 expression and marker genes of tumor infiltration-associated immune cells, including CD8+T cells (CD8A and CD8B), B cell (CD19 and CD79a), and Myeloid dendritic cell (HLA-DPB1, HLA-DQB1, HLA-DRA, HLA-DPA1, CD1C, NRP1, and ITGAX)." (PMID 33083464, 2020). "CD8α+ DCs are a subset of conventional DCs that require the Batf3 transcription factor (in mice) for development and exhibit efficient cross-presentation of viral and tumor antigens enabling CD8+ T cell-mediated defense." (PMID 33238631, 2020). "Notably, an increase in the CD8α+ DC population was also observed in the TDLNs of AdIL-17A-transduced tumors compared to the control group at day 4 post tumor inoculation." (PMID 32770025, 2020). "Additionally, it is widely reported that exhausted CD8+ T cells also express CD8A but lose the ability to eradicate the tumor cell." (PMID 31979136, 2020). "Guadecitabine treatment increased both CD8a and IFNγ at the tumor site." (PMID 32106810, 2020). "Evaluation of tumor sections harvested from mice at day 14 (one day post-LY treatment) demonstrated reduced phosphorylation and nuclear translocation of the TGFβ signaling mediator, Smad2, indicating ALK5 signaling was attenuated in tumor tissue, specifically in the CD8α+ cells." (PMID 32273499, 2020). "Notably, correlative analyses with histopathological tumor characteristics including the infiltration of CD8a-positive cells point toward functional distinct marker-defined fibroblast subsets in UBC." (PMID 31937798, 2020). "CAR constructs are composed of (i) the single-chain variable fragment (scFv) of tumor antigen-specific Ab (Ab), (ii) a hinge region, (iii) the hydrophobic trans-membrane domain which is usually derived from CD8α or CD28 and (iv) the intracellular signaling moieties." (PMID 32707982, 2020). "In addition, CD8A in CD8T cells was also strongly related to BTLA expression, confirming the theory that the BTLA-HVEM complex signaling system promotes the tumor antigen-specific CD8 + T cells’ survival." (PMID 32793631, 2020). "Indeed, the results of an immunohistochemical analysis showed that increasing numbers of CD3+ and CD8a+ TILs infiltrated into the tumor area after DAC treatment." (PMID 32079180, 2020). "Since all OS tumours had CD8+ T-cell infiltration (of varying degrees) inferred from CD8A gene expression, we wanted to investigate the expression level of several T-cell inhibitory receptors PD-1, Tim-3, LAG-3, and CTLA4 using the RNA-seq data to assess the functional state of these CD8 + TILs." (PMID 30674975, 2019). "This confirms the crucial role of CD8α+ DCs in eliciting anti-tumor immunity." (PMID 30774630, 2019). "The expression of genes encoding immune checkpoint molecules, such as programmed cell death ligand 1 (PD‐L1), programmed cell death 1 (PD‐1), cytotoxic T‐lymphocyte antigen (CTLA)‐4, and CD8A, which is a marker of tumor‐infiltrating lymphocytes, was investigated." (PMID 31240875, 2019). "Intratumoral administration of TriMix mRNA vaccines, which do not encode tumor-associated antigens, activate CD8α+ DCs and tumor-specific T cells, thereby slowing tumor growth in mouse models." (PMID 31779642, 2019).
tumor (continued). "Baseline PET imaging of CD4+ and CD8a+ was conducted in the same panel of syngeneic mouse models prior to treatment with Sym021 to evaluate the predictive value of TIL imaging for treatment response across various tumor types." (PMID 31754392, 2019). "However, in mice receiving Fcmr−/− DCs, depletion of CD8α+ T cells resulted in accelerated tumor growth, that was similar to mice receiving Fcmr+/+ DCs." (PMID 31213601, 2019). "It is possible that some of the effects of the α-CD8a antibody may be mediated by depletion of CD8+ DCs that play a unique role in cross-presentation of tumor antigens on MHC class I." (PMID 30832732, 2019). "This indicated that aberrant mitochondria function may affect the expansion of CD8α+ DCs which hold great importance in CD8+ T cells mediated anti-tumor function in vivo." (PMID 30930893, 2019). "However, rats that only received JEKHT exhibited significantly higher tumor infiltration of CD8a+ T cells than rats receiving both TAM and JEKHT (P = 0.013)." (PMID 30640711, 2019). "Therefore, we developed positron emission tomography (PET) radiotracers for non-invasive detection of CD4+ and CD8a+ TILs in syngeneic mouse tumor models for preclinical studies." (PMID 31754392, 2019). "CD8a+ is mainly expressed on effector T cells but can also be found on regulatory T cells, natural killer cells and dendritic cells 43,44, all of which can be found at an early disease state in the tumor microenvironment 45,46." (PMID 31754392, 2019). "IL-10 is not a pan-inhibitory cytokine of inflammatory responses; it is known to activate and increase CD8α cytotoxic capacity which may be significant for anti-tumour responses." (PMID 30692549, 2019). "Unirradiated tumor in the P1C4+ Cion + CD8α group grew rapidly compared with the Comb group." (PMID 30774761, 2019). "IFN-I can promote the tumor antigen cross-presentation to naïve CD8+ T cells by stimulating DC (including CD8α+ DCs) maturation and migration to lymph nodes and thus clonal expansion and differentiation into cytotoxic effector CD8+ T cells indirectly." (PMID 31049360, 2019). "Second, co-localization of the CD3 and the CD8α marker within the tumor was demonstrated." (PMID 29930558, 2018). "Moreover, they showed enhanced antigen cross-priming by CD8α+ murine DCs relative to antigen alone, measured by induction of T cell proliferation, as well as protective anti-tumor immunity." (PMID 30619259, 2018). "In order to further investigate the immunological profile of the primary tumors in both the 4T1 + RAW264.7 and 4T1 inoculation group, immunohistochemistry for CD45, CD163, Ly6G and CD8a was performed on primary tumor sections at pre- (1 and 3 w p.i.)and metastatic (5 w p.i.)time points." (PMID 30111338, 2018). "While a significant increase in percentage of CD8β+ T cells was found at the tumor site (mean values: 39.7% in contrast to 13.3% for the PBMC samples), the proportion of CD4+ T cells expressing the CD8α+ activation molecule was significantly reduced within tumor isolates." (PMID 29930558, 2018). "Interestingly, a fourfold increase in the percentage of γδ T cells displaying the CD2+CD8α+ phenotype was detected in tumors compared with blood; mean values: 51.1% in tumor isolates in contrast to 12.8% for the PBMC samples." (PMID 29930558, 2018). "Recent studies revealed that damaged NAs released by dying cancer cells can be sensed as DAMP danger signals by PRRs present on CD8α dendritic cells (DCs) in tumor microenvironment (TME), leading to activation of cGAS-STING and/or RIG-I/MDA5 signaling pathways." (PMID 29686682, 2018). "Although not significant due to high animal to animal variation, a strong tendency toward an increased amount of CD4+FOXP3+ T cells expressing the CD8α activation marker was observed in the tumor when compared with circulating blood (mean values: 16.0 and 2.1%)." (PMID 29930558, 2018). "Fewer CD8α+ cDC1s were included in the CD45.1+ products in the spleens of tumor-bearing hosts." (PMID 29593283, 2018).
tumor (continued). "IL-2/CD40 mostly did not alter young or elderly tumor-associated DC subset proportions, relative to untreated mice, with the exception of a small, but significant, increase in cross-presenting CD8α+CD11b− cDCs in elderly tumors." (PMID 30560130, 2018). "This resulted in increased production of IFN-γ, IL-17, and CD8a and reduced tumor burden." (PMID 29067024, 2017). "Therefore, a potent and long-acting adjuvant that can promote CD8α + DC activities is highly desirable to enhance T cell priming and subsequent anti-tumour immunity." (PMID 28596706, 2017). "Interestingly, the accumulation of CD8a-targeting nanoparticles in the tumor-draining lymph nodes increases over the timeframe evaluated." (PMID 29170511, 2017). "Analysis of tumour-infiltrating DCs (TIDCs) revealed a marked increase in CD8α+ TIDCs within TSA tumours after 8GyX3 but not 20 Gy radiation, consistent with the requirement for IFNβ for recruitment to the tumour of CD8α+ DCs, essential for optimal priming of anti-tumour CD8+ T cells." (PMID 28598415, 2017). "However, cancer cells also boost anti-inflammatory immune cells and regulatory T cells (Treg) to restrict CD8α + DC activity thereby attenuating the activation of tumour-suppressive T cells." (PMID 28596706, 2017). "Next, we also examined the activation marker expression in DCs and found that the expression of co-stimulatory molecule and major histocompatibility complex (MHC) class I and II were substantially increased by LPS-CuS treatment with laser irradiation in the both CD8α+ and CD8α− DCs in tumor drLN." (PMID 29285274, 2017). "Tumor-bearing Batf3-/- knockout mice deficient in CD11c+CD8α+ dendritic cells failed to mount any antitumor response after NRTUA treatment." (PMID 28910406, 2017). "In mice, CD8a+ DCs (functionally similar to the BDCA3+ DCs in human) are the major subset for antigen cross-presentation which responsible for the activation of anti-tumor CD8+ T cell response." (PMID 27250027, 2016). "We have found that expression of CD8A, considered a marker of lymphocyte infiltration, is higher in patients with better prognosis, probably indicating an activation of immune response against the tumor." (PMID 26871478, 2016). "Moreover, MHC class I and II expression levels on CD8α+CD11c+ and CD8α−CD11c+ DCs in the spleen and tumor drLN were considerably up-regulated by the combination of OVA and pullulan, whereas they were not up-regulated by OVA alone." (PMID 27341129, 2016). "Indeed, a comparison between tumor and adjacent normal mucosa revealed that tumors significantly underexpressed HLA class I genes and CD8A, suggesting a poorer ability for antigen presentation and recognition." (PMID 26871478, 2016). "To investigate whether the tumours with high immune gene expression (as represented by CD8A expression) show low levels of GATA3, ESR1 and PGR, we scattered each of these proteins against CD8A RNAseq counts." (PMID 26729235, 2016). "Moreover, it has been demonstrated that CD8α+ DCs acquire tumor antigens in vivo by recognizing and binding exposed actin filaments of necrotic cells via the receptor DNGR-1 (CLEC9A)." (PMID 26690204, 2015). "The decrease in the levels of PRF1, a key effector molecule for cytolysis mediated by T and NK cells, in presence of CD8A and CD56 expression in PDAC suggests that the cytotoxic activity or the number of CD8+ T and NK cells may be reduced in the tumor." (PMID 25415223, 2014). "This cascade of interferons, where IFN-α/β produced by CD11c+ cells (presumably DCs and macrophages) enhances the cross-priming activity of CD8α+ DCs thereby stimulating the generation of IFN-γ-producing CD8+ T cells and, finally, tumor rejection, is well known from the field of tumor immunoediting." (PMID 24141602, 2014).
tumor (continued). "Careful utilization of exogenous type I IFN (IFN-α/β) administration may also be a valuable method of enhancing GVT responses because they play an important role in cross-presentation of tumor antigens on DCs, especially CD8α+DCs, and enhance CTL responses." (PMID 24600454, 2014). "In a murine model of mesothelioma expressing influenza virus hemagglutinin, as a membrane-bound neo-tumor Ag, one group has reported that both CD8α DC and CD11b DC from tumor-draining LN could cross-present membrane hemagglutinin." (PMID 24400008, 2013). "Similarly, IRF-8−/− mice, which are devoid of CD8α DC and pDC, display impaired capacity to cross-present both soluble and tumor cell-derived Ag." (PMID 24400008, 2013). "Since CD8α+ DCs are required for rejection, therapies favoring capture of tumor antigen by this subset may facilitate more effective tumor-specific T-cell responses." (PMID 20976125, 2010). "Interestingly, we observed a 3 fold decrease in the absolute percentage of CD4+ T cells and CD8a+ T cells infiltrating into the tumor after administration of PC61." (PMID 18431473, 2008). "Furthermore, it led to increased myeloid cell activation and CD8α T cell infiltration in the tumor." (PMID 39889712, 2025). "Apparently, NK cells and CD8+ T cells were both anti-tumor executioners in NC, with αCD8A and αNK1.1 significantly accelerating tumor growth, while αCSF1R retarded tumor growth conversely, which could be explained by immune-suppressive M2 macrophages dominancy in NC as has been deliberated." (PMID 40087771, 2025). "After confirmation of deletion of CD8 + T cells by anti-CD8α antibody being continued for 1 to 2 weeks, when mice were injected with anti-CD8α antibody at initial treatment, the significant anti-tumor effect observed in mice treated with GN + OBP-702 disappeared." (PMID 38316993, 2024). "In addition, the low expression of CD8A in tumor tissue could predict the low survival rate of patients with LIHC." (PMID 37325556, 2023). "The score of total lymphocytes (CD45+ cells), cytotoxic T cells (CD8α+ cells), exhausted T cells, Treg, neutrophils, DCs and mature NK cells are all significantly increased in the cardiac tissue collected from vaccinated mice when compared to naïve and tumor only controls." (PMID 37346042, 2023). "To analyze whether the ERSGs scoring system was associated with ICB therapy, we further explored the relationship between ERSGs score and several well-known ICB response predictors, such as tumor mutation burden (TMB), MSI status, PD-L1, CD8A, TIDE score, TIS, and COX-IS." (PMID 37821882, 2023). "Thus, we stained the tumor tissue collected from mice in the WT and Ccng2−/− groups for CD8a." (PMID 36566226, 2022). "Importantly, anti-CD8α antibody abolished the increase in tumor-infiltrating CD8 T cells (Cd8a), as well as the increase in Ifng, which is produced by tumor-infiltrating CD8 T cells and could be an important contributor to tumor regression." (PMID 36187936, 2022). "In line with this picture, baseline levels of the immune markers CD8 (a potential surrogate marker for cytotoxic tumor-infiltrating T-lymphocytes) and PD-L1 had a moderate predictive impact on pCR under anti-HER2 therapy, whether measured by IHC or by mRNA assessment." (PMID 34638369, 2021). "The expression levels of CD8A (encoding CD8, marker of CD8+ T cells), CD4 (encoding CD4, marker of CD4+ T cells), and CD3D (encoding CD3, marker of T cells) were also significantly high in the low-risk groups, indicating higher abundance of the tumor suppressor T-cell subpopulation." (PMID 34641822, 2021). "In addition, TEG011_CD8α cells successfully cleared tumor cells in the bone marrow." (PMID 34759930, 2021). "Transfer of CD8αβ in combination with intermediate affinity tumor reactive αβTCR has been reported to support tumor control in vitro and in vivo, and for high affinity αβTCR with artificial signaling domains adding CD8α alone has been shown to reprogram CD4+ T cells." (PMID 34759930, 2021).